CXCL8 (C-X-C motif chemokine ligand 8)
Diseases named in the same sentence as CXCL8 in open-access papers (continued):
Sharing a sentence is not in itself a finding about the gene and the disease.
periodontitis (continued). "Thus, this study aimed to investigate the IL-1β, CXCL8, and TNF-α levels in GCF in patients with different degrees of periodontitis and PISF in patients with healthy implants." (PMID 33726736, 2021). "We also found that the circulating lymphocytes and monocytes CXCL8/IL8 mRNA levels of periodontally healthy subjects were significantly lower when compared to patients affected concomitantly by T2DM, dyslipidemia and periodontitis." (PMID 32424199, 2020). "This enhances the production of diverse inflammatory mediators, including IL-6, CXCL8, and CCL2, which may contribute to the overwhelming immune response and consequently to progression of periodontitis." (PMID 31178663, 2019). "IL-6, CXCL-8, and TNF-α may have an important role in the pathogenesis of chronic periodontitis and detection of these cytokines may be beneficial to identify periodontitis patients." (PMID 29670909, 2018). "On the one hand, the production of IL-6, CXCL8, and CCL2 might promote inflammatory response in periodontitis." (PMID 27504628, 2016). "Also, although salivary sTLR2 augments IL-8 (CXCL8) production in monocytes, there is evidence for diminished levels of sTLR2 in periodontitis saliva." (PMID 24944840, 2014). "Moreover, chemokines such as CXCL8, CXCL10, CXCL12, and CCL5 accumulate in the crevicular fluid of periodontitis patients and their source might be attributed to fibroblasts at least for CXCL2, CXCL3, CXCL8, CXCL9, CXCL10, CXCL12, and CXCL16." (PMID 37762294, 2023). "In our study, we focused on the expression of three proteins, IL-6, CXCL8, and CCL2, which are thought to play an essential role in periodontal tissue inflammation and are usually regarded as the factors which enhance the inflammatory response in periodontitis." (PMID 31178663, 2019). "Therefore, the gingival tissue and crevicular fluid of patients with chronic periodontitis have been reported to contain significantly increased amounts of CCL3, also known as macrophage inflammatory protein- (MIP-) 1α and CXCL-8/IL-8, as compared to healthy subjects." (PMID 29507865, 2018). "Further, individuals with and without periodontitis were used as controls and it was found that H&N carcinomas give rise to a change in the chemokine composition of the oral fluid with a significant increase in CXCL8, CXCL10, and CCL14 before therapy, a finding that was not reproduced after therapy." (PMID 24376459, 2013).
colorectal cancer (284 papers, 2002 to 2026). A primary or metastatic malignant neoplasm that affects the colon or rectum. "CXCL8 has been implicated in colorectal cancer, where serum CXCL8 expression was identified as a potential diagnostic biomarker with high diagnostic accuracy." (PMID 40087784, 2025). "The C-X-C motif chemokine ligand 8 (interleukin-8, IL-8) has been identified as the most extensively and significantly upregulated chemokine in colorectal cancer (CRC), and seems to be associated with drug resistance." (PMID 38891846, 2024). "CXCL8 has also been connected to weight loss in pancreatic cancer, stomach cancer, and colorectal cancer patients." (PMID 35159388, 2022). "CXCL1 and CXCL8 that are associated with colorectal cancer risk and overall survival, appeared to be included in epithelial cell signaling in Helicobacter pylori (H. pylori) infection, chemokine signaling pathway and cytokine-cytokine receptor interaction." (PMID 30642095, 2019). "Several studies showed CXCL8 overexpression obviously associated with poor overall and disease-free survival in colorectal cancer patients." (PMID 28883082, 2017). "Some studies have indicated that CXCL8 is associated with poor prognosis in colorectal cancer." (PMID 39706835, 2024). "However, CXCL8 has been implicated as having a role in colorectal cancer by acting as an autocrine growth factor in colon carcinoma cell lines as well as promoting cell division and possible migration by cleaving metalloproteinase molecules." (PMID 33809994, 2021). "High expression of CXCL8 in colorectal cancer is part of the Myc/CXCL8/tissue inhibitor of metalloproteinase 1 (TIMP1) oncogenic mark." (PMID 40076892, 2025). "EGCG treatment inhibited STAT3 and CXCL8 expression and NETs formation in colorectal cancer-derived neutrophils." (PMID 41019086, 2025). "The presence of CXCL8 protein in the serum of colorectal cancer patients is notably higher than that in healthy control histones, influencing tumor stage and metastasis in these patients." (PMID 38275602, 2024). "We found recently in colorectal cancer patients that such massive dead cell accumulations stain positive for caspase-cleaved cytokeratin 18 and CXCL8/IL-8, indicating that they derive from apoptotic tumour cells, which release a neutrophil chemoattractant." (PMID 38218739, 2024). "CXCL8 and its receptors (CXCR1, CXCR2, and Duffy antigen receptor for chemokines (DARC)) are associated with the development of colorectal cancer and its liver metastases." (PMID 37142825, 2024). "IL-8/C-X-C motif ligand 8 (CXCL8) is a chemokine often overexpressed in colorectal cancers, supporting migration, invasion, angiogenesis and metastasis, and has been associated with a decreased overall survival and progression-free survival." (PMID 39167197, 2024). "For example, SAA1 produced by colorectal cancer cells recruits neutrophils to the invasive front of colorectal cancer, and stimulates neutrophils to produce CXCL8 and MMP-9, which contribute to tumor progression." (PMID 37081987, 2023). "It was recently discovered that CXCL8 is a good blood marker in the progression of colorectal cancer." (PMID 36902343, 2023). "The aim of this work is to evaluate the level of CXCL8 in the tumor as a marker of progression in colorectal cancer (CRC)." (PMID 36517518, 2022). "CXCL8 (also known as IL-8) is a major inflammatory mediator and it’s receptors are highly connected with the development of various colorectal cancer and its liver metastases as well as it enhances the major human neutrophils conscription." (PMID 36016137, 2022). "CXCL8 and its receptors contributed to the survival, proliferation, migration and invasion of circulating tumor cells, in addition to promoting colorectal cancer liver metastasis through the induction of EMT in cancer cells." (PMID 35922850, 2022). "The results showed that the high expression of CXCL8 suggested the poor prognosis of colorectal cancer." (PMID 35845924, 2022).
colorectal cancer (continued). "Blocking the JNK/CXCL8 pathway enhances radiation-induced necroptosis and radiotherapy efficacy in colorectal cancer." (PMID 35011369, 2021). "Here, we identified the TME-related gene CXCL8 in a high-ImmuneScore population that contributed to better survival in colorectal cancer (CRC) patients from The Cancer Genome Atlas (TCGA) database." (PMID 34025668, 2021). "The results from nine datasets indicated that the mRNA expression levels of CXCL8 were significantly upregulated in patients with colorectal carcinoma." (PMID 34233297, 2021). "The seven significant colorectal cancer associated genes shortlisted from the differentially expressed genes were CALD1, CTNNB1, CXCL14, PTCH1, CXCL8, TNFAIP3, and NNMT after mapping with PubMed, OMIM, MeSH, and PMC databases." (PMID 32523911, 2020). "The expression of selected genes related to MG degradation III (AKR1B10, AKR1C2 and ADH4), glyoxalase system (GLO1 and HAGH), glucose transport (SLC2A1 and SLC5A1) and colorectal cancer-associated genes (AREG, CXCL8 and CEACAM1) were quantitated using qRT-PCR." (PMID 32561807, 2020). "CXCL8 enhanced resistance to anoikis in colorectal cancer cells, promoted castration-resistant through PI3K/AKT/mTOR pathway and regulating cyclin D1 in prostate cancer cells." (PMID 30723697, 2018). "Both CXCL8 and CXCL10 are chemoattractants that have been implicated in colorectal cancer progression." (PMID 28717003, 2017). "As per cancer cell migration, CXCL8 is known to generate a chemotactic gradient stimulating the motility of colorectal carcinoma in a mechanism involving the expression of αVβ6 integrins." (PMID 26284488, 2015). "CXCL8 signaling is a major pro-inflammatory signal in multiple solid tumors including breast and colorectal cancers, diseases in which 5-FU is currently used or recommended as standard-of-care for metastatic disease." (PMID 22590561, 2012). "Overexpression of STAT3 promoted CXCL8 production and NETs formation in colorectal cancer patients." (PMID 41019086, 2025). "Hence, based on the artificial analysis, we detected critical genes involved in colorectal cancer, including IL-1β, IL-2, CXCL8, and FN1." (PMID 38637796, 2024). "The superoxide dismutase (SOD2)-CXCL8-neutrophil recruitment axis may be a potential factor in the progression of colorectal cancer." (PMID 39100676, 2024). "Among them, CCL20 and CXCL8, both of which could promote the migration and metastasis of colorectal cancer cells, were validated to be upregulated by F. nucleatum infection." (PMID 37814323, 2023). "Additionally, the expression of CXCL8 and its receptors was found to enhance the angiogenesis, proliferation, migration, invasion, and survival of colorectal cancer cells and induce the EMT and metastasis of colorectal cancer cells." (PMID 35303800, 2022). "Similarly, CXCL8 promotes tumor growth and metastasis and predicts bad outcomes in colorectal cancer." (PMID 36072669, 2022). "Furthermore, CXCL8 is extensively expressed in colorectal cancer, and promotes proliferation, migration, invasion, and angiogenesis of colorectal cancer cells." (PMID 36295640, 2022). "CXCL8 is an inflammatory chemokine elevated in the colorectal cancer (CRC) tumour microenvironment." (PMID 35879507, 2022). "The human colorectal cancer-derived HCT116 cell line has been shown to upregulate CXCL8 (IL-8) and CXCL1 in response to F. nucleatum ATCC 23726 and may contribute to metastatic spread." (PMID 34700376, 2021). "CXCL8 enhances cell migration through increasing integrin αvβ6 expression in colorectal cancer." (PMID 35011369, 2021). "Therefore, the CXC family plays an important role in the development of colorectal cancer, especially CXCL8, CXCL3, and CXCL1." (PMID 32462020, 2020). "Gene Expression Profiling Interactive Analysis (GEPIA) overall survival (OS) has shown that low expressions of AQP8, ZG16, CXCL3, and CXCL8 may predict poor survival outcome in colorectal cancer." (PMID 32462020, 2020).
colorectal cancer (continued). "The results of OS analysis have shown that low expressions of AQP8, ZG16, CXCL3, and CXCL8 may predict poor survival outcome in colorectal cancer." (PMID 32462020, 2020). "The OS analysis of 10 core genes was performed by using the GEPIA tool website, and the results show that low expressions of AQP8, ZG16, CXCL3, and CXCL8 may predict poor survival outcome in colorectal cancer." (PMID 32462020, 2020). "Gene Expression Profiling Interactive Analysis (GEPIA) overall survival (OS) analysis has shown that low expressions of AQP8, ZG16, CXCL3, and CXCL8 may predict poor survival outcome in colorectal cancer." (PMID 32462020, 2020). "Therefore, CXCL8 can be used as a predictor for tumor prognosis, at least for pancreatic and colorectal cancers." (PMID 29147073, 2017). "Thus, we observed for the expression levels of CXCL8, CXCL1 and CXCL5 a significant association with the development of colorectal carcinoma and also CRLM." (PMID 18578857, 2008). "Similarly, colorectal cancer tumorspheres showed increased mRNA levels of CXCL8 and IL6R." (PMID 39336151, 2024). "In addition, CXCL1 and CXCL8 promote the migration of colorectal cancer cells." (PMID 39595551, 2024). "In addition, a colorectal cancer study showed CXCL8 alone could predict early-stage colorectal cancer accurately." (PMID 35632517, 2022). "Serum CXCL8 may be a potential biomarker of colorectal cancer progression." (PMID 34439306, 2021). "However, the function of CXCL8 in colorectal cancer (CRC) is controversial." (PMID 32038715, 2019). "But some other studies suggested IL-8 was not linked with tumor progression and worse prognosis in colorectal cancer, and CXCL8-positivity in the tumor infiltrate might be associated with a statistically significant reduction in the risk of disease recurrence." (PMID 25856316, 2015). "Indeed, CXCL8 has been shown to be down-regulated in response to sulindac and has been identified as a mediator of sulindac-induced apoptosis in colorectal cancer cell line models, while salicylate-treatment results in the down-regulation of CXCL8 expression in the macrophage-like cell line THP-1." (PMID 24276377, 2013). "CXCL8 reportedly may function as an important therapeutic target in colorectal cancers." (PMID 23800251, 2013). "Compared to healthy subjects, STAT3 and CXCL8 mRNA expression was increased in neutrophils from colorectal cancer patients, as was STAT3, p-STAT3 and CXCL8 protein expression." (PMID 41019086, 2025). "There is evidence that the upregulation of NOX4, CXCL8, CXCL5, GDF15, and MMP13 genes in colorectal cancer promotes the metastasis of cancer cells, so a sustained upregulation of these genes after aspirin treatment will not benefit from treatment." (PMID 41425852, 2025). "Mast cells have a pivotal role in the progression of colorectal cancer through the release of granules containing angiogenic factors such as VEGF-A, CXCL8, MMP-9, and lymphangiogenic factors like VEGF-C and VEGF-D." (PMID 38683136, 2024). "AC modulates the CXCL8/CXCR2 chemokine axis and inhibits the PI3K/Akt/mTOR pathway in colorectal cancer cells and orthotopic mouse models, thereby exerting anti-metastatic effects on HCC." (PMID 39206194, 2024). "In this study, we conducted differential gene expression analysis on three GEO datasets and confirmed SPP1, MMP1, CXCL8, CXCL1, TIMP1, MMP3, and CXCL10 as core regulatory genes in colorectal cancer through a protein-protein interaction network." (PMID 37842645, 2023). "For example, in colorectal cancer tissue, CXCL1, CXCL2, CXCL3, CXCL5, CXCL8, and CXCL11 were highly expressed, while CXCL12, CXCL13, and CXCL14 were little expressed." (PMID 36612163, 2022). "Tumorous CXCL8 mediates increased NETs formation in the TME, promoting colorectal cancer liver metastasis." (PMID 35011369, 2021). "CAFs can attract monocytes by secreting CXCL8 to enhance TAM enrichment and suppress NK cells’ function in colorectal cancer." (PMID 35011369, 2021).
colorectal cancer (continued). "Quantitative RT-PCR results have shown that the following 3 core genes were significantly different between colorectal cancer tissues and normal colorectal tissues: SST, CXCL8, and MS4A12." (PMID 32462020, 2020). "Moreover, serum CXCL-8 might be a potential biomarker of colorectal cancer progression." (PMID 32192002, 2020). "Analysis using qRT-PCR has shown that SST, CXCL8, and MS4A12 were significant differentially expressed between colorectal cancer tissues and normal colorectal tissues (P < 0.05)." (PMID 32462020, 2020). "The close interplay among these mediators is demonstrated by the up-regulation of CXCL5 and CXCL8 expression in human non-small cell lung cancer cells and of CXCL1 in colorectal cancer cells induced by PTGS2." (PMID 31920649, 2019). "We showed here higher serum levels of IL1B, IL6, CXCL8, TNFA, CCL2 and tumor levels of IL1B, IL6, CXCL8, TNFA in colorectal cancer, suggesting the involvement of these inflammatory factors in colorectal cancer." (PMID 31528237, 2019). "Based on a known synergistic relationship between CXCL8 and CCL20 that promotes poor survival outcome in colorectal cancer, these two genes were further investigated as possible prognostic factors in GBM." (PMID 29983870, 2018). "For instance, the two well-known SASP factors, CXCL8/IL-8 and CCL2/MCP-1, increase the migration of colorectal cancer cells." (PMID 27907906, 2016). "Additionally, Chemokine 8 (CXCL8) induces M2 macrophage polarization and inhibits CD8T cell infiltration, creating an immunosuppressive microenvironment in colorectal cancer." (PMID 39100676, 2024). "Hence, the relative expression of the IL-1β, IL-2, CXCL8, and FN1 was overexpression by colorectal cancer and administration of 5-FU." (PMID 38637796, 2024). "Similarly, we found recently that apoptotic colorectal cancer cells secrete CXCL1, CXCL5, and CXCL8 in response to chemotherapeutic drugs such as oxaliplatin, 5-FU, or bortezomib." (PMID 37957750, 2023). "The effect of NT on IL-8/CXCL8 expression may depend on NF-κB activation, as demonstrated by transfected NCM460-line colonocytes and HCT116 human colorectal cancer." (PMID 37298595, 2023). "CAF-secreted IL-6 and CXCL8 induce Bromodomain-containing protein 4 (BRD4) protein expression and lead to chromatin remodeling and Bromodomain and Extraterminal (BET) inhibitor resistance in colorectal cancer (CRC)." (PMID 35011369, 2021). "To date, increasing number of studies indicated that CXCL8 and its receptors were overexpressed in several types of human cancers, including colorectal cancer, prostate cancer, cervical cancer and non-small cell lung cancer." (PMID 32766720, 2020). "In addition, 3 core genes (SST, CXCL8, and MS4A12) were found to be significantly differentially expressed between colorectal cancer tissue and normal colorectal tissue using qRT-PCR." (PMID 32462020, 2020). "CXCL8 is an angiogenic factor in many cancers, CCL20 promotes malignancy, and together they synergize to promote a poor survival outcome via induction of epithelial-mesenchymal transition in colorectal cancer." (PMID 29983870, 2018). "Also, the effect of NT on IL-8/CXCL8 expression may depend on NF-κB activation as demonstrated by transfected NCM460-line colonocytes and HCT116 human colorectal cancer." (PMID 29467963, 2018). "For example, in gastric cancer, CXCL8 promotes an immunosuppressive microenvironment by inducing macrophages.Targeting the CXCL8-CXCR2 axis may hinder dendritic cell activation or recruitment, which in turn exerts a critical anti-tumor effect on colorectal cancer." (PMID 38532933, 2024). "Furthermore, in human colorectal carcinoma cells, the transcription factor SNAIL which plays a critical role in regulating EMT also regulates the expression of the chemokine CXCL8, which further demonstrates the importance of CXCL8 or IL-8 in the process of EMT in cancer." (PMID 24259307, 2013).
colorectal cancer (continued). "It has been shown that CXCL8 has a negative correlation with the expression of Bcl-2-related cell death protein (BAD), thus inhibiting the apoptosis of colorectal cancer cells." (PMID 33688358, 2021). "CXCL8 is overexpressed in multiple cancer types, including nonsmall cell lung cancer (NSCLC), breast, pancreatic, and colorectal cancers." (PMID 29147073, 2017).